RN7SKP247 (RN7SK pseudogene 247)
Gene: Miscellaneous RNA gene on chromosome 1 (81,251,789 to 81,252,096, forward strand). Ensembl gene ENSG00000223026.
Homologues: Orthologues: chimpanzee 7SK (81% identical), guinea pig 7SK (53% identical). Paralogues in human: RN7SKP133 (69% identical), RN7SKP189 (69% identical), RN7SKP240 (69% identical), 7SK (69% identical), RN7SKP255 (68% identical), RN7SKP79 (68% identical), RN7SKP176 (68% identical), RN7SKP230 (68% identical), RN7SKP180 (68% identical), RN7SKP47 (68% identical), RN7SKP203 (67% identical), RN7SKP217 (67% identical), and 283 more.